IGFBP1 (insulin like growth factor binding protein 1)
Description:
Multifunctional protein that plays a critical role in regulating the availability of IGFs such as IGF1 and IGF2 to their receptors and thereby regulates IGF-mediated cellular processes including cell migration, proliferation, differentiation or apoptosis in a cell-type specific manner. Also plays a positive role in cell migration by interacting with integrin ITGA5:ITGB1 through its RGD motif. Mechanistically, binding to integrins leads to activation of focal adhesion kinase/PTK2 and stimulation of the mitogen-activated protein kinase (MAPK) pathway. Regulates cardiomyocyte apoptosis by suppressing HIF-1alpha/HIF1A ubiquitination and subsequent degradation (By similarity).
Synonyms: PP12; IBP1; IGF-BP25; AFBP; hIGFBP-1
Tractability: Small molecule: it belongs to a druggable protein family. Antibody: UniProt places it where antibodies can reach, with high confidence; its Gene Ontology location is reachable by antibodies, with high confidence; UniProt predicts a signal peptide or a membrane-spanning region. PROTAC: its protein half-life has been measured; a small molecule that binds it is known.
Target class: Secreted protein
Gene: Protein-coding gene on chromosome 7 (45,888,360 to 45,893,660, forward strand). Ensembl gene ENSG00000146678.
Subcellular location: Secreted
Subcellular location (Human Protein Atlas): Golgi apparatus; Predicted to be secreted
Pathways (Reactome):
Metabolism of proteins: Post-translational protein phosphorylation; Regulation of Insulin-like Growth Factor (IGF) transport and uptake by Insulin-like Growth Factor Binding Proteins (IGFBPs)
Cellular responses to stimuli: ATF4 activates genes in response to endoplasmic reticulum stress
Gene expression (Transcription): FOXO-mediated transcription of oxidative stress, metabolic and neuronal genes
Gene Ontology:
Molecular function: insulin-like growth factor I binding; insulin-like growth factor II binding; protein binding; insulin-like growth factor binding; signaling receptor binding
Biological process: negative regulation of canonical Wnt signaling pathway; regulation of insulin-like growth factor receptor signaling pathway; signal transduction; insulin receptor signaling pathway; positive regulation of cell growth; tissue regeneration
Cellular component: extracellular region; endoplasmic reticulum lumen; non-collagenous component of interstitial matrix
Genetic constraint (gnomAD): Loss-of-function variants: 31 observed, 21.69 expected, observed/expected ratio (o/e) 1.43, 90% interval 1.07 to 1.86. The upper end of that interval is the gene's LOEUF score, 1.86, which puts it in group 6 of 6, group 1 being the genes least tolerant of losing a copy. Missense variants: 298 observed, 261.86 expected, observed/expected ratio (o/e) 1.14, 90% interval 1.03 to 1.25. Synonymous variants: 135 observed, 117.82 expected, observed/expected ratio (o/e) 1.15, 90% interval 1 to 1.32.
Homologues: Orthologues: chimpanzee IGFBP1 (99% identical), macaque IGFBP1 (93% identical), guinea pig IGFBP1 (71% identical), rat Igfbp1 (70% identical), pig IGFBP1 (69% identical), mouse Igfbp1 (68% identical), rabbit IGFBP1 (67% identical), tropical clawed frog igfbp1 (46% identical), zebrafish igfbp1a (40% identical), zebrafish igfbp1b (35% identical). Paralogues in human: IGFBP2 (33% identical), IGFBP4 (29% identical), IGFBP3 (28% identical), IGFBP5 (27% identical), IGFBP6 (25% identical).
Diseases named in the same sentence as IGFBP1 in open-access papers:
IGFBP1 is named in the same sentence as 216 diseases in open-access papers, as found by Europe PMC text mining. Sharing a sentence is not in itself a finding about the gene and the disease. The quoted sentences say what the papers report.
Insulin resistance (88 papers, 2007 to 2026). Increased resistance towards insulin, that is, diminished effectiveness of insulin in reducing blood glucose levels. "IGFBP-1 has been implicated in hepatic insulin resistance, and lower serum IGFBP-1 levels have been associated with improved glucose tolerance in human clinical studies." (PMID 40286436, 2025). "asserted that TXNDC5 induces insulin resistance and increases the risk of diabetes mellitus (DM) by inhibiting the expression of insulin-like growth factor binding protein-1 (IGFBP1)." (PMID 38629066, 2024). "Higher circulating IGFBP1 levels were associated with greater insulin sensitivity (lesser insulin resistance) at ~26 weeks gestation in the same cohort and in two additional pregnancy cohorts." (PMID 38627562, 2024). "In humans, weight loss, reductions in hepatic fat and hepatic insulin resistance and, consequently, reductions in circulating insulin are associated with increases in IGFBP-1, which we also observed in our study in patients with low IGFBP-1 levels at baseline." (PMID 38928106, 2024). "Chronically increased levels of insulin decrease circulating IGFBP-1, which correlates closely with whole-body and hepatic insulin resistance as well as with metabolic dysfunction-associated steatotic liver disease (MASLD)." (PMID 38928106, 2024). "Higher circulating IGFBP1 levels were strongly associated with greater insulin sensitivity (lesser insulin resistance) at ~ 26 weeks' gestation in the same cohort and two additional pregnancy cohorts." (PMID 37961187, 2023). "This reinforces the fact that IGFBP-1 can be used as a marker of insulin resistance in children at high risk." (PMID 35586622, 2022). "In summary, low IGFBP-1 can be detected during childhood with a high risk for the development of insulin resistance." (PMID 35586622, 2022). "Disorders characterized by insulin resistance, such as obesity, metabolic syndrome and type 2 diabetes mellitus, are associated with a reduction in serum IGFBP-1 levels." (PMID 33436773, 2021). "To investigate if loss of IGFBP-1 predisposes to obesity-related glucose intolerance and insulin resistance, we challenged IGFBP-1-KO mice and their wild-type littermate controls with a 60% high-fat diet for 8 weeks." (PMID 32190801, 2020). "Obesity is associated with insulin resistance and hyperinsulinemia, which reduce the levels of insulin-like growth factor binding protein 1 (IGFBP-1) and insulin-like growth factor binding protein 2 (IGFBP-2)." (PMID 24587258, 2014). "Low serum IGFBP-7 levels are related to low IGFBP-1 and subsequently associated with insulin resistance in T2D." (PMID 24180466, 2013). "IGFBP1 sequesters IGF1 reducing bioavailability and an increased IGF1:IGFBP1 ratio and reduced IGFBP1 in serum is associated with obesity, hyperinsulinemia and insulin resistance in human studies and in women with PCOS." (PMID 21935484, 2011). "Insulin resistance is a common symptom observed in obese women, and it may be associated with miscarriage through the reduction of insulin-like growth factor-binding protein-1 and uterine αvβ3 integrin." (PMID 38433972, 2023). "IGFBP1 has previously been linked to diabetes/insulin regulation, as lower circulating levels of IGFBP1 have been associated with impaired glucose tolerance, insulin resistance, diabetes, and cardiovascular diseases in mouse models." (PMID 36287121, 2022). "Low circulating IGFBP1 is associated with insulin resistance, diabetes, and cardiovascular disease." (PMID 35614477, 2022). "IGFBP-1 may constitute as an independent risk factor for the development of insulin resistance, increased risk of type 2 diabetes, and other adiposity-related comorbidities in children, even at a young age." (PMID 35586622, 2022). "Furthermore, elevated insulin levels, insulin-like growth factor binding protein-1, and greater insulin resistance were associated with Anti-β2GP1 levels." (PMID 36050731, 2022).
Insulin resistance (continued). "Notably, both LPA and IGFBP-1 have been suggested to be inversely associated with insulin resistance." (PMID 36260611, 2022). "It is therefore also possible that a loss of glomerular IGFBP-1 expression could contribute towards podocyte insulin resistance in type 2 diabetes." (PMID 33758952, 2021). "However, the inverse association between both EDIH and EDIP with IGFBP-1 is intriguing, as lower IGFBP-1 has been associated with risk of insulin resistance, type 2 diabetes, obesity, and cardiovascular disease in human and rodent studies." (PMID 34616762, 2021). "A recent study in a leukemic mouse model showed that increased levels of insulin-like growth factor binding protein 1 (IGFBP1), an adipokine produced in adipocytes, were associated with insulin resistance and that giving these mice insulin decreased serum IGFBP1 levels." (PMID 33437503, 2020). "Having excluded an obligatory role for IGFBP-1 in maintaining normal metabolism, we next investigated whether loss of circulating IGFBP-1 predisposes to obesity-induced glucose intolerance and insulin resistance, as suggested by human observational data." (PMID 32190801, 2020). "Low IGFBP-1 is associated with hepatic insulin resistance and hyperinsulinemia." (PMID 32934313, 2020). "Insulin resistance is associated with hyperinsulinemia and low circulating IGFBP1 levels." (PMID 29049355, 2017). "Furthermore, a series of epidemiological studies during the past two decades has linked low circulating IGFBP-1 concentrations with insulin resistance, type 2 diabetes, and CVD." (PMID 25461385, 2014). "The correlation between IGFBP-7 and IGFBP-1 suggests that low IGFBP-7 may be associated with insulin resistance in T2D." (PMID 24180466, 2013). "Similarly, markers of insulin resistance, such as high circulation levels of C-peptide and insulin-like growth factor-binding protein 1(IGFBP-1), were showed to be directly associated with colorectal cancer risk." (PMID 22087284, 2011). "Thus, increased insulin signalling in early diabetes, prior to the development of glomerular insulin resistance, may suppress FoxO1 activity and IGFBP-1 expression in the glomerulus and associated signalling." (PMID 33758952, 2021). "The cause of these shifts has been attributed to relative protein malnutrition and the impact of stimulators of IGFBP-1, including proinflammatory cytokines, as well as hepatic insulin resistance." (PMID 40188287, 2025). "In hepatic insulin resistance, the relationship between IGFBP-1 and insulin changes, with higher concentrations of insulin required to suppress IGFBP-1 secretion." (PMID 39595651, 2024). "This appears to relate to the progression of hepatic insulin resistance, which reduces the suppression of the hepatokine IGFBP-1 relative to circulating insulin levels." (PMID 38928106, 2024). "In this study, phosphorylated IGFBP-1 correlated inversely with fasting insulin, and homeostatic model assessment-insulin resistance (HOMA-IR)." (PMID 39595651, 2024). "In obesity, with peripheral insulin resistance and, therefore, decreased responsiveness to insulin-mediated glucose disposal or adipose tissue lipolysis, insulin concentrations increase and IGFBP-1 is suppressed." (PMID 39595651, 2024). "In our cohorts, we observed similar inverse associations of IGFBP-1 with IHL, VAT, hepatic, and whole-body insulin resistance, reflecting extensive metabolic impairment." (PMID 38928106, 2024). "Low IGFBP-1, high CRP and low IGF-I are independently associated with the presence of WHO-defined metabolic syndrome and insulin resistance in different ethnic groups (n = 440, mean 51 y, ~50% F)." (PMID 39595651, 2024). "In the presence of peripheral insulin resistance, i.e., decreased responsiveness to insulin-mediated glucose disposal or adipose tissue lipolysis, insulin concentrations increase and IGFBP-1 is suppressed." (PMID 39595651, 2024).
Insulin resistance (continued). "The group who had GDM with both insulin resistance and insulin deficiency (mixed defect GDM) showed an IGFBP1 trajectory that was intermediate between the other GDM subtypes." (PMID 38627562, 2024). "IGFBP-1 in children can identify the presence of insulin resistance in the group with BMI 1 to 2 SDS, even before the known markers of insulin resistance such as elevated triglycerides and even before decreased HDL and adiponectin levels are identified." (PMID 35586622, 2022). "Circulating concentrations of IGFBP-1, coupled with fasting levels of insulin, have been proposed as a more specific screening test for insulin resistance in children." (PMID 35586622, 2022). "This cross-sectional study revealed the role of IGFBP-1 as an independent marker of insulin resistance and adiposity in this cohort of multiethnic diverse groups of schoolchildren." (PMID 35586622, 2022). "Toddlers who were small for gestational age at birth have an increased lifetime risk of development of type 2 diabetes, and they also have significantly lower IGFBP-1 levels even before manifesting insulin resistance." (PMID 35586622, 2022). "The cutoff value of IGFBP-1 levels of <5 had a sensitivity of 94% and a specificity of 67% to identify insulin resistance in children." (PMID 35586622, 2022). "We propose that IGFBP-1 should be considered as marker of insulin resistance in children, and it is easier to obtain than other commonly used indices of insulin sensitivity." (PMID 35586622, 2022). "Our data indicate that by measuring IGFBP-1, the practitioners will have a reliable marker of insulin resistance." (PMID 35586622, 2022). "At a state of obesity and insulin resistance, levels of fasting IGFBP1 were significantly reduced and this functioned as a predictive biomarker for developing abnormal glucose regulation." (PMID 34646401, 2021). "IGFBP1 is strongly regulated by insulin and decreased in subjects with insulin resistance and was inversely correlated with insulin levels, waist circumference and abdominal fat content in this study." (PMID 33686453, 2021). "HMGA1 deficiency causes insulin resistance and diabetes through impairing the transcription of the insulin receptor gene INSR and of the insulin-like growth factor binding protein-1 (IGFBP-1) genes." (PMID 31963852, 2020). "Regardless of the gestational diabetes status, in all of the pregnant women studied, a low IGFBP-1 level was related to increased insulin resistance, as also detected in our study." (PMID 32923723, 2020). "In pre-pubertal children with obesity, low levels of circulating IGFBP1 and adiponectin are strong predictors of insulin resistance and metabolic complications." (PMID 33266497, 2020). "Lower level of insulin-like growth factor-binding protein (IGFBP-1) has been observed in insulin resistance, while higher level of matrix metalloproteinase-8 (MMP-8) has been linked to obesity." (PMID 32923723, 2020). "In pre-pubertal children with obesity, low circulating IGFBP-1 is a strong predictor of insulin resistance and metabolic complications." (PMID 33266497, 2020). "Overexpression of human IGFBP-1 in IRKO mice ameliorated the detrimental effect of insulin resistance on recovery from hindlimb ischemia and vascular density in ischemic muscle." (PMID 32190801, 2020). "Metformin had beneficial effects on maternal serum IGFBP-1 concentrations compared to insulin, possibly due to its favorable effect on insulin resistance." (PMID 32652973, 2020). "Further investigation of other factors affecting IGFBP-1 interactions and insulin resistance is required, in this case, IGF-1." (PMID 30775682, 2018). "Previous studies have shown that IGFBP-1 induced improved glucose regulation and increased insulin sensitivity is a part of protective mechanism induced upon insulin resistance in the body." (PMID 30627105, 2018).
Insulin resistance (continued). "Excessive adiposity‐induced insulin resistance and compensatory hyperinsulinemia have been shown to decrease hepatic synthesis of IGFBP‐1, which translates into increased concentrations of bioavailable IGF‐1, without modifications in serum total IGF‐1 levels." (PMID 26443692, 2016). "With increasing insulin resistance, in overt T2DM, the IGFBP1 level increased, which caused a significant decrease in free IGF-1 concentration." (PMID 28031898, 2015). "It should be noted that in obese patients with weak insulin resistance the free IGF-1 level increased insignificantly due to the lowered IGFBP1 level, while total IGF-1 level was maintained." (PMID 28031898, 2015). "One hundred twenty-five children (73.1%) had high HOMA-IR and low IGFBP-1, interpreted as indicating whole-body insulin resistance and hepatic IR." (PMID 25411786, 2014). "In obese children there are strong inverse relationships between IGFBP-1 concentrations and insulin resistance, as well as the metabolic syndrome." (PMID 26237614, 2014). "In the whole cohort, the change in insulin resistance between baseline and after 1 year of study medication was inversely correlated with changes in IGFBP1 (r=−0.28; P=0.001) and directly correlated with changes in IGF1 (r=0.22; P=0.01)." (PMID 24026893, 2013). "Insulin resistance leads to a compensatory increase in portal insulin secretion, which suppresses IGFBP-1 concentrations." (PMID 23840881, 2013). "In a study comparing it with other simple indices of insulin resistance in normal glucose-tolerant subjects, IGFBP-1 was suggested to be the most reliable marker." (PMID 24278739, 2012). "Their serum fasting insulin, fasting glucose, insulin-like growth factor-1, adiponectin, IGFBP-1, triglyceride concentrations, and the homeostasis assessment model for insulin resistance (HOMA-IR) were evaluated." (PMID 23186039, 2012). "Decreased adiponectin and IGFBP-1 levels and increased triglyceride levels are considered to reflect impaired insulin sensitivity and predict insulin resistance." (PMID 23186039, 2012). "In support of its use in this context, serum IGFBP-1 levels have been shown to correlate with the gold standard method for assessing insulin resistance, namely, the hyperinsulinaemic, euglycaemic clamp." (PMID 24278739, 2012). "From earlier studies it is known that obesity, low levels of IGFBP-1 and an increased IGF-1:IGFBP-1 ratio are factors associated with insulin resistance in men and women." (PMID 17212815, 2007). "Enhancements in inflammatory and metabolic indicators, such as decreased TNF-α, IL-6, and insulin resistance, may facilitate ideal endometrial gene expression profiles associated with implantation, including integrins, HOXA10, IGFBP-1, and angiogenic pathways." (PMID 41596408, 2026). "Insulin-like growth factor-binding protein (IGFBP)-1 is a marker of insulin resistance." (PMID 40188287, 2025). "In a cross-sectional study in children aged 11–15 years (42% female), low IGFBP-1 was an independent marker of insulin resistance (determined by fasting insulin and response to intravenous glucose) and was better than elevated triglycerides and decreased HDL and adiponectin levels." (PMID 39595651, 2024). "If hepatic insulin resistance and inflammation are dominant features, IGFBP-1 concentrations will be relatively high and may predict poor outcomes." (PMID 39595651, 2024). "Other mechanisms include increased insulin resistance induced by high-dose glucocorticoids that increases intra-portal insulin, decreases IGFBP-1 that increases free IGF-I, and direct glucocorticoid effects in increasing hepatic IGF-I synthesis and decreasing hepatic insulin clearance." (PMID 39665021, 2024). "However, the IGFBP-1 level is known to increase with the progression of T2D despite persistent hyperinsulinemia due to a progressive hepatic insulin resistance." (PMID 37762544, 2023).